TTC39A (tetratricopeptide repeat domain 39A)
Synonyms: DEME-6; C1orf34; KIAA0452
Tractability: No criterion of Open Targets' tractability assessment is met for any kind of drug.
Gene: Protein-coding gene on chromosome 1 (51,287,258 to 51,345,116, reverse strand). Ensembl gene ENSG00000085831.
Subcellular location (Human Protein Atlas): Centrosome
Gene Ontology:
Cellular component: centrosome
Genetic constraint (gnomAD): Loss-of-function variants: 46 observed, 78.45 expected, observed/expected ratio (o/e) 0.59, 90% interval 0.46 to 0.75. The upper end of that interval is the gene's LOEUF score, 0.75, which puts it in group 3 of 6, group 1 being the genes least tolerant of losing a copy. Missense variants: 542 observed, 700.6 expected, observed/expected ratio (o/e) 0.77, 90% interval 0.72 to 0.83. Synonymous variants: 254 observed, 270.5 expected, observed/expected ratio (o/e) 0.94, 90% interval 0.85 to 1.04.
Homologues: Orthologues: chimpanzee TTC39A (98% identical), macaque TTC39A (96% identical), pig TTC39A (94% identical), rabbit TTC39A (93% identical), mouse Ttc39a (92% identical), rat Ttc39a (92% identical), guinea pig TTC39A (91% identical), dog TTC39A (90% identical), tropical clawed frog ttc39a (72% identical), zebrafish ttc39a (67% identical), Caenorhabditis elegans ttc-39B (36% identical). Paralogues in human: TTC39B (52% identical), TTC39C (23% identical).
Diseases named in the same sentence as TTC39A in open-access papers:
TTC39A is named in the same sentence as 4 diseases in open-access papers, as found by Europe PMC text mining. Sharing a sentence is not in itself a finding about the gene and the disease. The quoted sentences say what the papers report.
diabetes (1 paper, 2020). "However, as there are multiple transcript variants described for Ttc39a, which encode distinct isoforms, the specific role of the differently expressed isoform in the pathogenesis of diabetes in mice has to be clarified." (PMID 33133152, 2020).
liver disease (1 paper, 2024). "The consistent upregulation of Trem2, Anxa2, Ttc39a, and Gdf15 across all stages of liver disease—from steatosis and NASH to fibrosis—suggests that these genes play a pivotal role in the progression of NAFLD." (PMID 39697329, 2024).
steatosis (1 paper, 2024). Increased lipid within the cytoplasm of cells. "We also analyzed the expression levels of Trem2, Anxa2, Ttc39a, and Gdf15 across various stages of the disease, including steatosis, NASH, and fibrosis." (PMID 39697329, 2024).
tumor (2 papers, 2023 to 2024). "High expression of ANXA2, TREM2, TTC39A, and GDF15 may lead to a more suppressive tumor microenvironment and enhanced immune escape, thereby reducing the efficacy of immunotherapy." (PMID 39697329, 2024).